IL6 (interleukin 6)
Diseases named in the same sentence as IL6 in open-access papers (continued):
Sharing a sentence is not in itself a finding about the gene and the disease.
Cirrhosis (continued). "Low-grade cirrhosis-associated immune dysfunction is present in cirrhotic patients without ACLF and is characterized by the production of pro-inflammatory cytokines such as Il-1β, IL-6, TNF-α and INF-γ." (PMID 39861356, 2025). "SB reduced the serum concentrations of TNF-α, IL-1β, IL-6, and IL-4 in animals with metabolic dysfunction-associated steatotic liver disease (MASLD); lowered the serum TNF-α and IL-6 levels in experimental cirrhosis in rats; and reduced the CRP levels in decompensated cirrhosis." (PMID 39203520, 2024). "Sweat monitoring nocturnal CRP/IL6 elevations in cirrhosis versus controls." (PMID 39733165, 2024). "From the Hedge’s G values for the three sweat biomarkers, it can be concluded that CRP and IL6 show a significant effect size between evening and night periods in cirrhosis subjects compared to morning periods, while the same significance in effect size is not observed in control subjects." (PMID 39733165, 2024). "Elevated sweat IL6 may be an important predictor of mortality and larger studies are indicated to further characterize inflammatory sweat biomarkers in cirrhosis." (PMID 39733165, 2024). "Moreover, patients with cirrhosis or alcoholic hepatitis have been shown to have elevated blood concentrations of IL-6." (PMID 39290493, 2024). "Nevertheless, IL6 was only slightly elevated in the different cirrhosis models." (PMID 39451225, 2024). "Indeed, reduced expression of miR-29a and miR-29b has been associated with increased concentration of IL-6 and TNF-α and more advanced grades in patients with cirrhosis." (PMID 39125612, 2024). "Also, in patients with decompensated cirrhosis, there is a marked increase in proinflammatory cytokines such TNFα and IL-6." (PMID 38551716, 2024). "IL-6 exhibited a significant positive association with ALT, AST, and HBV-DNA copies in chronic hepatitis and HCC groups, as well as a significant positive correlation with serum creatinine in cirrhosis and HCC groups." (PMID 39071840, 2024). "HGF, IL-6, and IL-8 levels were increased in patients, with ∼2-fold higher levels in patients with cirrhosis versus healthy, while platelet derived growth factor-BB (PDGF-BB) and regulated on activation, normal T cell expressed and secreted (RANTES) showed lower concentrations compared to controls." (PMID 38015590, 2023). "Therefore, HBx is considered to be an IL-6 upregulator that promote development of cirrhosis via an IL-6-mediated increase in expression of microRNA-21." (PMID 35119591, 2023). "Interestingly, while patients with compensated cirrhosis (Child-Pugh class A) showed an inflammatory profile with myeloid cells producing the proinflammatory cytokines IL-6 and TNF, decompensated patients produced reduced levels of these cytokines." (PMID 37928515, 2023). "In addition, increasing levels of inflammatory cytokines such as interleukin (IL)-6 and tumor necrosis factor-alpha (TNF-α) trigger the inflammatory immune response and predispose patients with cirrhosis to infectious complications such as sepsis." (PMID 36983211, 2023). "IL-33 treatment of neutrophils from patients with cirrhosis improves their chemotaxis towards IL-842 and IL-6 has been reported to increase neutrophil migration towards IL-8; however, it does not influence neutrophil apoptosis, priming or adhesion molecule expression." (PMID 37822786, 2023). "In addition, patients with cirrhosis often have systemic inflammation and significantly high levels of pro-inflammatory factors such as IL-1β, IL-6, and TNF in vivo." (PMID 37881635, 2023). "Increased levels of the proinflammatory cytokines tumor necrosis factor-alpha (TNFa), interleukin-1, and interleukin-6 might influence the hemodynamic alterations of patients with cirrhosis." (PMID 35269779, 2022). "Levels of LPS, IL-6, and IL-8 were higher in patients with cirrhosis than in the healthy controls." (PMID 35130114, 2022).
Cirrhosis (continued). "Furthermore, patients with chronic HBV infection and cirrhosis had significantly higher plasma IL-6 levels and more severe liver inflammation." (PMID 36389814, 2022). "To assess the relationship between members of the circulating microbiome and systemic inflammation, we measured the levels of lipopolysaccharide (LPS), interleukin (IL)-6, and IL-8 in both compartments of patients with cirrhosis and in the peripheral veins of the healthy controls." (PMID 35130114, 2022). "At the same time, inflammatory markers (i.e., CRP and IL-6), along with RAS components, were elevated with more severe ACLD, indicating a state of coagulation/fibrinolysis activation linked to RAS activity—that reportedly is upregulated in cirrhosis." (PMID 34945736, 2021). "In the present study, despite no incidences of cirrhosis or extrahepatic obstruction of the portal vein, splenic enlargement was associated with higher serum IL-6." (PMID 31951598, 2020). "Rifaximin could reduce the concentrations of TNF-α, IL-6, and endotoxin in patients with decompensated cirrhosis." (PMID 32759852, 2020). "Targeting anticoagulation and anti-inflammation (IL-6) may be promising therapeutic strategies for cirrhosis with PVT." (PMID 32351989, 2020). "C. longa markedly decreased the hepatic interleukin-6 (IL-6) value in C57BL/6 mice administered alcohol and an MCD diet, which are models that demonstrate the important role of IL-6 in the development of alcoholic or nonalcoholic fatty liver into cirrhosis or cancer." (PMID 32802138, 2020). "Overall, these findings suggested that IL-6 may be responsible for the proinflammatory effects as a consequence of an improvement by PVT in cirrhosis." (PMID 32351989, 2020). "Ex vivo: Microarray gene expression profiling of PBMCs from ARLD cirrhosis (DC) compared to HC, showed increased induction of pro-inflammatory cytokine genes (IL-6, IL-8, TNFα), but decreased induction of type-1 and type-2 IFN-stimulated genes, compared to HC (see right column)." (PMID 30804947, 2019). "Moreover, patients with alcoholic hepatitis and cirrhosis showed elevated serum concentrations of these cytokines, including IL-6 and IL-8, where expression levels correlated with markers of liver function and clinical outcome." (PMID 29849889, 2018). "Similarly, elevated levels of salivary IL-1β, IL-6, and secretory IgA in cirrhosis patients have also been reported." (PMID 29969462, 2018). "Also serum IL-6 levels were also found to be elevated in patients with chronic liver disease including cirrhosis and HCC." (PMID 27034885, 2016). "TNF-α and IL-6 levels could be used to differentiate between patients with compensated cirrhosis and patients with de-compensated alcoholic cirrhosis." (PMID 26343741, 2015). "Theoretically, higher levels of IL6 in chronic hepatitis and cirrhosis might promote HCC through increasing SPINK1." (PMID 23527199, 2013). "Our data therefore supports the use of IL-6, along with leukocyte count, CRP, bilirubin, and serum creatinine, as potential biomarkers to monitor disease progression and the inflammatory burden associated with EF DNA positivity in patients with decompensated cirrhosis and ACLF." (PMID 41189884, 2025). "The level of plasma IL-6 may increase with the progression of cirrhosis." (PMID 40872617, 2025). "Acute spikes in systemic inflammation before AD may, for example, result in a final rise in portal pressure to trigger variceal hemorrhage, and serum interleukin-6 (IL-6) concentration has been demonstrated as an independent predictor of decompensation in outpatients with cirrhosis." (PMID 39194320, 2024). "Indeed, serum levels of the pro-inflammatory cytokine interleukin-6 (IL-6), tumor necrosis factor-α (TNF-α), C-reactive protein, and lipopolysaccharide are elevated in patients with cirrhosis in parallel with the severity of disease, and are associated with poor outcomes." (PMID 35545763, 2022).
Cirrhosis (continued). "IL6 is a multibiological characteristic cytokine located on human chromosome 7p21, which is not only widely presented in various types of inflammations as a common inflammatory factor but also played important roles in multiple stages and systems of biology, such as cirrhosis." (PMID 35479581, 2022). "Additionally, we found a feedback loop between TSG-6, MMP12 and pro-inflammatory cytokines (TNF-α, IL-6, and IL-1β), which may improve our understanding of the aggravating process of cirrhosis and antifibrotic mechanisms of TSG-6 and MSCs." (PMID 31903104, 2020). "BPC 157 significantly counteracted an increase in proinflammatory and procachectic cytokines, such as interleukin 6 (IL-6) and TNF-alpha (a similar effect also appeared in rats with bile duct ligation and cirrhosis treated with BPC 157 therapy)." (PMID 40573323, 2025). "IL-6, CD163, and vWF were higher (p <0.01) at baseline in patients with cirrhosis and CSPH compared to those with subclinical PH and controls." (PMID 39850960, 2025). "Chronic Inflammation and Oxidative Stress: Chronic liver disease, such as in MASH or cirrhosis, activates Kupffer cells and other immune cells, resulting in the release of pro-inflammatory cytokines (e.g., TNF-α, IL-6) and oxidative stress." (PMID 40001516, 2025). "Systemic Inflammation and Oxidative Stress: Chronic liver injury, such as MASH or cirrhosis, activates Kupffer cells and other immune cells, resulting in the release of pro-inflammatory cytokines (e.g., TNF-α, IL-6) and oxidative stress." (PMID 40001516, 2025). "Other studies have reported that tumor necrosis factor-alpha (TNF-α), a key marker of cirrhosis and HCC development, is correlated with the secretion of IL-6." (PMID 41219858, 2025). "Among these cytokines, IL-6 and IL-8 are of particular relevance because their excessive production has been related to a worse prognosis and ACLF development in patients with cirrhosis." (PMID 40431335, 2025). "Furthermore, clinical studies have indicated that in patients with cirrhosis, circulating butyrate levels have a moderate to strong significant negative correlation with key inflammatory mediators, LPS and IL-6 (LPS: RS = −0.58; IL-6: RS = −0.49; both p < 0.001)." (PMID 41332466, 2025). "Inflammatory cytokines such as interleukin-6 (IL-6) and tumor necrosis factor-alpha (TNF-α) also play important roles in the progression of cirrhosis and are involved in the complications such as HE and HCC." (PMID 41149065, 2025). "In contrast, CRP, PCT, and the average levels of IL-6 and IL-10 are higher in ACLF than in patients with decompensated cirrhosis." (PMID 39337069, 2024). "Studies which stimulated monocytes or PBMCs from patients with cirrhosis or healthy controls with LPS ex vivo have indicated higher level of TNF-α, IL-1β and IL-6 production in the former." (PMID 38413535, 2024). "In hepatic cirrhosis, TLR4-LPS interaction determines TNF, IL-1, IL-6 pro-inflammatory cytokines, and chemokines production." (PMID 38473721, 2024). "Similarly, the HBV viral load (p=0.03, OR = 2.45, and 95% CI: 1.69–3.65), IL-6 levels (p=0.04, OR = 3.45, and 95% CI: 2.01–6.9), and TRL2 variants (p=0.01, OR = 4.25, and 95% CI: 2.14–13.5) are independent risk factors associated with disease progression from cirrhosis to HCC." (PMID 39071840, 2024). "Among compensated versus decompensated cirrhosis, the average decompensated sweat biomarker values measured during the study period were slightly higher in both CRP and IL6." (PMID 39733165, 2024). "Next, we detected plasma inflammatory mediators (IL-6, IL-10, TNF-α, IL-8 and IL-12p70) in patients with cirrhosis and controls." (PMID 38413535, 2024). "In patients with cirrhosis, rifaximin has been demonstrated to increase mean arterial pressure and GFR, while decreasing plasma endotoxin, serum interleukin-6, and serum tumor necrosis factor-α." (PMID 37626668, 2023).
Cirrhosis (continued). "Here, patients with decompensated cirrhosis had significantly higher serum levels of Int-α2, Int-γ, TNF-α, IL-6, IL-8, IL-10, IL-23, and IL-33 compared to compensated patients, both in blood obtained from hepatic and jugular veins." (PMID 38077228, 2023). "An increase in IL-6 and TNF-α levels in patients with cirrhosis is involved in CRP production, suggesting that changes in CRP are linked to changes in these inflammatory cytokines." (PMID 36983211, 2023). "In line with previous work, we found concentrations of IL-6 and IL-8 to be increased in patients with NAFLD and HCC, with the highest levels in the sera of patients with cirrhosis." (PMID 38015590, 2023). "A higher trend of pro-inflammatory cytokines including IL-1α, IL-1β, IL-6, IL-8, IFN-γ and TNF-α was detected in the plasma from ACLF patients than that from cirrhosis patients, as well as the anti-inflammatory cytokines including IL-4, IL-10 and IL-13." (PMID 37380987, 2023). "Serum from HCV-HCC patients showed higher levels of MMP-2 and pentraxin-3 as well, but, in addition, exhibited increased levels of IL-6 and HGF in HCC compared to HCV-cirrhosis patients." (PMID 36230823, 2022). "Some studies focused on the secretion of IL-1, IL-6, TNF, TGF-β, and other cytokines due to splenomegaly, which leads to the formation of cirrhosis." (PMID 36211271, 2022). "According to qRT-PCR, levels of the proinflammatory cytokines (IL-1β, TNF-α, and IL-6) were extremely increased in ACLF patients compared with those in HCs and cirrhosis patients, which suggested a hyperinflammatory state in the liver of ACLF patients." (PMID 35629036, 2022). "To understand the interplay between regulatory RNA and inflammatory markers observed in cirrhosis and HCC, we evaluated levels of sCD14, sCD163, IL-6, MCP-1, IP10, Mac2BP, and ATX." (PMID 36138741, 2022). "Growing evidences revealed higher levels of IL6, TNFα, IL1β, and IL10 in HCC patients with cirrhosis compared with those infected with HBV or HCV in the absence of cirrhosis." (PMID 32164265, 2020). "The most significant biomarkers to detect the presence of Child-Pugh B cirrhosis (CTP 7–9) were IP-10 (p-value= 0.008) and IL-6 (p-value=0.002)." (PMID 32587340, 2020). "The NLR has been described widely as a predictor of HA bacterial infections in decompensated cirrhosis, and it correlates with tumor necrosis factor alpha (TNF-α) and interleukin 6 (IL-6) concentrations." (PMID 32155772, 2020). "Patients with Child-Pugh B cirrhosis (CTP 7–9) had higher plasma values of IP-10, IL-6, OPG, sVCAM-1, sICAM-1, and D-dimer (p-value <0.05 and q-value <0.1) than patients with Child-Pugh A cirrhosis (CTP < 7)." (PMID 32587340, 2020). "The underlying mechanism by which abnormal hepatic function, inflammation activation, and the elevation of IL-6 level were induced directly by PVT establishment, aggravating cirrhosis or both needed to be demonstrated in additional studies." (PMID 32351989, 2020). "Circulating monocytes from patients with AD and ACLF compared with stable cirrhosis demonstrated reduced expression of HLA-DR and attenuated production of TNF-α/IL-6 in response to lipopolysaccharide (LPS), which has previously been linked to adverse outcome." (PMID 31822557, 2020). "Since serum HMGB1 and IL-6 can accumulate in urine during AKI-associated inflammatory processes, both could be useful in the differential diagnosis of the causes of AKI in cirrhosis patients—especially between parenchymal renal disease and functional AKI—similar to other urinary biomarkers." (PMID 33061824, 2020). "In our population of ICU patients with cirrhosis, about one third had varying levels for NUTRIC and mNUTRIC with IL6 ≥ 400 pg/mL." (PMID 32709104, 2020). "Some studies have shown potential effects of Cit on reducing inflammatory markers such as tumor necrosis factor α (TNF-α) and interleukin-6 (IL-6), which can prevent development of disease to severe conditions such as NASH and cirrhosis." (PMID 30767788, 2019).
Cirrhosis (continued). "Earlier studies showed increased serum levels of interleukin 6 (IL-6) and interleukin 10 (IL-10) in patients with ACLF compared to those of patients with stable cirrhosis, in a manner similar to that reported in patients with severe sepsis." (PMID 27578545, 2016). "Plasma IL6 and CCL2 were significantly increased in the bariatric population compared to lean controls, while high levels were detected in patients with cirrhosis which is in keeping with previous publications from our group." (PMID 27992443, 2016). "The correlation between IL-6 levels and the presence of MHE were found in both patients with HBV related cirrhosis(r = 0.54, P =." (PMID 26039496, 2015). "First, these results confirm and extend the positive correlation established between basal IL-6 levels and ERK phosphorylation in peritoneal M-DM from patients with cirrhosis." (PMID 22866973, 2012). "In contrast to its protective effect, several human and animal studies have demonstrated that IL-6 is elevated in alcoholic liver disease, NAFLD, NASH, and cirrhosis." (PMID 22514624, 2012). "We recently described the primed status of peritoneal macrophages in cirrhosis, finding it to be related to ERK1/2 phosphorylation and IL-6 secretion." (PMID 22866973, 2012). "Cirrhotic rats had significantly higher levels of proinflammatory cytokines including TNF-α, IL-1β and IL-6, and soluble ICAM-1, which have been shown to play important roles in development of cirrhosis." (PMID 22022478, 2011). "Although we have previously shown that pathological IP is accompanied by increased levels of LBP and IL‐6 in patients with cirrhosis, unexpectedly, we herein did not observe significantly higher LBP levels in patients with acute decompensation or ACLF." (PMID 40317887, 2025). "In summary, metabolic dysfunction that influences liver health, which can lead to cirrhosis, includes altered fatty acid oxidation, the appearance of mediators such as TNF-α and IL-6, a reduction in the liver synthesis of insulin-like growth factor-1 (IGF-1), and insulin resistance in the liver." (PMID 40806358, 2025). "Of the patients with compensated cirrhosis without a history of AD (n = 97), 48 (49.4%) showed normal plasma levels of IL-24 and IL-6." (PMID 39337069, 2024). "In order to evaluate IL-6 as a potential marker to diagnose SBP, we performed two different survival analyses including all patients with cirrhosis despite their PMN count, divided by serum IL-6 and ascites IL-6 cut-offs as calculated before (serum IL-6: 442.37 pg/mL, ascites IL-6: 2.0 × 105 pg/ml)." (PMID 38962151, 2024). "Our study provides intriguing evidence that continuous noninvasive monitoring of inflammatory biomarkers may predict outcomes – as patients with cirrhosis had higher evening and nocturnal levels of sweat CRP and IL6 when compared with healthy controls." (PMID 39733165, 2024). "Furthermore, the administration of rifaximin for 4–12 weeks has been shown to decrease the blood levels of IL-6, IL-10, and TNF-α in patients with nonalcoholic fatty liver disease and cirrhosis with HE." (PMID 36983211, 2023). "For example, activated hepatic macrophages produce cytokines, such as IL-6, IL-1β, TNF-α and macrophage colony-stimulating factor (M-CSF), which sustain their pro-cirrhosis and pro-inflammatory activities while also stimulating HSCs to form an inflammatory cascade." (PMID 38275754, 2023). "Furthermore, IL-6 levels were significantly higher in patients with CSPH, which is one of the main drivers for life-threatening complications in cirrhosis such as bleeding of esophageal varices." (PMID 38077228, 2023). "Fourth, it is hypothetical that rifaximin improves liver functional reserve by improving systemic inflammation in patients with cirrhosis because inflammatory cytokines such as IL-6 and TNF-αand endotoxins were not evaluated in this study." (PMID 36983211, 2023).